IL10 (interleukin 10)
Diseases named in the same sentence as IL10 in open-access papers (continued):
Sharing a sentence is not in itself a finding about the gene and the disease.
infection (continued). "The increased relative expression of the IL10 gene, which encodes an immunosuppressive cytokine, may also result in the suppression of host innate immune responses to infection resulting in mycobacterial persistence within the host." (PMID 25206354, 2014). "Surprisingly, T cell-specific and complete IL-10-deficient mice displayed a significantly (p<0,01) increased footpad swelling, compared to macrophage/neutrophil-specific IL-10-deficient mice and Cre− control animals, as soon as one week after infection." (PMID 23825956, 2013). "However, in in vivo models of infection with T. cruzi, the cardiac expression of IL-10 has been associated with the extent of the inflammatory infiltrates present in the heart." (PMID 24260222, 2013). "Interestingly, the T cell-specific as well as the complete IL-10-deficient BALB/c mice also showed an increased footpad swelling early after infection, comparable to the respective IL-10 mutant mice on a C57BL/6 background." (PMID 23825956, 2013). "This is supported by the findings that in vivo depletion of pDCs resulted in higher inflammatory cytokine response, but decreased elicitation of Tregs and IL-10 production that was associated with extensive lung pathological changes and unresolved disease following Cpn infection." (PMID 24386207, 2013). "Some of them have shown that IL-10 mediates susceptibility to infection by T. cruzi." (PMID 24260222, 2013). "A dysregulated TH1 response and subsequent tissue damage are also observed in IL-10-deficient mice following infection with other pathogens, including Leishmania major, Trypanosoma cruzi, Plasmodium chabaudi, Listeria monocytogenes, murine cytomegalovirus, and respiratory influenza virus." (PMID 23755052, 2013). "Furthermore, IL-10 levels were hardly detected in the blood of TLR2-deficient animals during infection." (PMID 24058538, 2013). "Furthermore, we provided evidence that IL-10-deficient mice showed early production of Th1-related antibodies, predicting the onset of a less severe infection." (PMID 24205424, 2013). "Because of the temporal relationship, we concluded that anti-GIPL IgG1 responses earlier in infection could potentially cause increased parasite burdens later in infection due to IL-10 suppression of a Th1 response." (PMID 23675550, 2013). "However, IL-10 release attenuated in the livers of TLR2-deficient mice from 1 d post-infection and significantly reduced by 70% at 3 d post-infection (vs. WT mice)." (PMID 24058538, 2013). "However, early in infection (2 weeks), IL-10-deficient mice showed significantly higher titers of IgG1, IgG2a, and IgG2b, suggesting the development of mixed Th1/Th2 responses." (PMID 24205424, 2013). "Furthermore, the overexpression of IL-10 under control of the MHC class II Ea promoter resulted in the increased susceptibility of the mice to infection with L. major, supporting a role for IL-10 derived from professional APC." (PMID 23825956, 2013). "Following infection with L. major, the T cell-specific and complete IL-10-deficient mice on the C57BL/6 as well as the BALB/c background are characterized by an increased early inflammation, which is due to the enhanced secretion of IFN-γ by CD4+ as well as CD8+ T cells." (PMID 23825956, 2013). "We, and others, have previously demonstrated that Mtb susceptibility in CBA/J mice is mediated by excessive pulmonary IL-10 during infection, yet the underlying mechanism remains unclear." (PMID 23472214, 2013). "Consequently, these observations indicate that TNF-α and IL-10 protect significant proportions of mice from fatal infection by pathogenic JaOArS982 virus." (PMID 23940775, 2013). "Chickens vaccinated with profilin plus ISA 71 and infected with all 3 Eimeria parasites had greater levels of intestinal IEL gene transcripts encoding IFN-γ, IL-2, IL-10, and/or IL-17A at 3 days post-infection compared with infected birds vaccinated with profilin alone." (PMID 23593150, 2013).
infection (continued). "Subjects with untreated chronic HCV infection have elevated serum levels of IL-10 and disease association studies of IL-10 promoter polymorphisms indicate that IL-10 levels are important in both susceptibility to infection and resistance to inflammatory disease." (PMID 23561395, 2013). "Using transgenic mice expressing human IL-10 (Il10−/−/hIL10BAC), we could investigate the role of cellular-specific IL-10 production on susceptibility to infection." (PMID 21811511, 2012). "Whether IL-10-producing B cells induced by B. microti infection are directly responsible for enhanced susceptibility to infection by this protozoan parasite was determined using the B cell-deficient mouse strain μMT, which lacks mature B cells." (PMID 23071588, 2012). "We also examined whether this increased susceptibility to infection might occur through the tolerogenic effects of increased levels in the systemic circulation of the immune regulatory cytokine IL-10, in early life." (PMID 22848773, 2012). "The authors suggested that the induction of IL-10 by several other PRRSV strains may be associated with their ability to induce pro-inflammatory cytokines during the acute phase of infection." (PMID 22909062, 2012). "The capsule of serotype 2, the most common serotype associated with infection in humans and pigs, was highly anti-phagocytic and modulated the IL-10/IL-12 and IL-10/TNF-α cytokine production in favor of a more anti-inflammatory profile compared to other serotypes." (PMID 22558240, 2012). "We hypothesized that the increased susceptibility to infection through having an infected mother could be mediated by IL-10, an immune modulatory cytokine that is produced by regulatory cells." (PMID 22848773, 2012). "IL-10 can dampen a damaging pro-inflammatory response and has previously been associated with schistosome infection levels where it can limit pathology during infection as is suggested in the case of bladder pathology." (PMID 23145202, 2012). "This increased susceptibility to infection could be explained by the fact that host IgG on the amastigote surface ligates the macrophage FcγRs and induces IL-10 production by macrophages." (PMID 21811511, 2012). "Moreover, studies using IL-10-deficient mice showed increased mortality during the acute phase of infection, confirming the important role of simultaneous induction of regulatory cytokines." (PMID 22952678, 2012). "Furthermore, adoptive transfer of IL-10-producing B cells induced by B. microti infection led to increased susceptibility of recipient mice to infection with B. microti." (PMID 23071588, 2012). "To dissect the consequences of IL-10 deficiency on liver inflammation after infection, we first quantitated the number of inflammatory foci in livers using hematoxylin and eosin (H&E) stained liver sections taken from uninfected and MCMV-infected WT and IL-10−/− mice." (PMID 22880122, 2012). "However, especially in the later course following trauma, the incidence of infection is strongly associated with systemic IL-10 concentrations." (PMID 22046081, 2012). "The IL-10 cytokine has an important role as an immunoregulator of the infections caused by Plasmodium, by neutralizing the effects of the other cytokines produced by Th1 and CD8 cells, which are responsible for much of the immunopathology associated with the overproduction of IFN-γ." (PMID 21917128, 2011). "Gene-targeting of the IL-10 and IgA-encoding genes synergizes to clear the infection, i.e. IL-10-/-/IgA-/- mice clear H. pylori infections better than IL-10-/- mice, both under conditions of experimental infection of naive as well as previously vaccinated mice." (PMID 22044597, 2011). "To determine whether IL-10 was contributing to the persistence of the infection in our mice, we compared fungal burdens and cytokine profiles in wild-type and IL-10-deficient animals 7 days after infection." (PMID 21575914, 2011).
infection (continued). "Our demonstration that systemic IL-10 levels were significantly higher in Magaya (the high infection areas) and that they were inversely related to auto-reactive antibody levels in both villages is consistent with IL-10 being associated with immuno-modulation of host responses.." (PMID 21573157, 2011). "Consequently, acquired susceptibility of C57BL/6 mice to oeGAPDH infection was completely reverted in IL-10-deficient animals." (PMID 22114550, 2011). "Th2-associated cytokines, such as IL-4 and IL-10, appear relatively late after infection and may limit immune pathology." (PMID 21957440, 2011). "So to understand the interplay between the disease healing inflammatory cytokines IFN-γ, and IL-12 and disease associated cytokines IL-10 and IL-4, we sought to investigate Ag-specific in vitro production of cytokines before and after challenge infection in both STP and LTP studies." (PMID 21311597, 2011). "It is possible that the independent association between increased IL-10 TT responses and household socio-economic status might be mediated by repeated, unmeasured, exposures to infection." (PMID 21040693, 2010). "Moreover, production of IL-10 during the early acute phase of infection is associated with an increased proportion of splenic CD4+CD25+ T cells in non-lethal P. yoelii infection." (PMID 19680449, 2009). "In the early phase of infection cytomegalovirus causes release of IL-10." (PMID 17488493, 2007). "Furthermore, different early proinflammatory cytokine responses, as well as exaggerated increases in IL-10, are associated with later onset of infections." (PMID 16280065, 2005). "Additionally, by suppressing immune responses by producing IL-4 and IL-10, MQs may increase the susceptibility of this organ to various types of infection." (PMID 39582867, 2024). "Silent or subclinical infections have been associated with powerful antiviral responses, early and robust innate immune responses, specific HLA genes, and specific gene expression patterns, such as higher plasma levels of the anti-inflammatory cytokines IL-10, IL-1RA and IL-19." (PMID 39531435, 2024). "Though IL-27, along with IL-10, has been shown to enhance nasal colonization and increase susceptibility to S. aureus pneumonia, its role in suppressing inflammation in the later stages of infection may be beneficial in CC024 mice." (PMID 39178306, 2024). "Interestingly, as demonstrated in our previous articles, ST2−/− mice also showed a reduction in IL-10 levels from the acute to the chronic phase of the infection, which may also be associated with the exacerbated inflammatory response developed by this strain." (PMID 37373379, 2023). "Moreover, the cytokine and chemokine patterns show a more evident mix of Th1 and Th2 response during the late phase of envenoming associated with the secondary infection inflammation, assigning some molecules, as IL-6 and IL-10, as possible novel markers for wound infection prediction." (PMID 37755950, 2023). "Differently, the T helper-2 (Th2) response with IL-4 and IL-10 production can result in the inhibition of macrophage activation, with a consequent increase in the intracellular replication of the parasite and, therefore, an increased susceptibility to infection and the development of severe disease." (PMID 37764934, 2023). "Thus, the NI cohort may be more susceptible to infections as their increased circulating IL-10 inhibits antigen presentation preventing stimulation of T cell immunity." (PMID 35958579, 2022). "Moreover, the anti-inflammatory cytokines IL-4 and IL-10 inhibit the production of pro-inflammatory cytokines, and decreased production of IL-4 and IL-10 may increase susceptibility to infections and lead to PTB." (PMID 35860261, 2022). "IL-10 is an anti-inflammatory cytokine, and its down-regulation may be associated with inefficient regulation of inflammatory processes, thereby increasing the lungs’ vulnerability to incur damage following infection or injury." (PMID 35415078, 2022).
infection (continued). "In this context, new emerging diagnostic and prognostic markers of infection could be useful in the prediction of the disease severity, as well as pro and anti-inflammatory cytokines involved in the cytokine storm, such as IL-6 and IL-10." (PMID 35740951, 2022). "Nevertheless, the production of IL-10 by the host would also protect host cells in the acute pro-inflammatory immune response, caused either by damage induced by the parasite in the early state of the infection or by liver damage, at least in this experimental model." (PMID 34943041, 2021). "The early infection (3 dpc) triggered a strong transcriptional up-regulation of many immune genes in different organs including those encoding pro-inflammatory cytokines IL-1β, IL-6 and TNFα and other cytokines involved in the development of adaptive immunity (IL-8, IL-10, IL-22, IL-17C2, INFγ)." (PMID 34497310, 2021). "In addition, IL-10 orchestrates the reversal of Th1/Th2 immune dominance during infectious disease pathogenesis and progression, and earlyIL-10 production has been associated with host’s susceptibility towards infection." (PMID 33562617, 2021). "Interestingly, healthy FPR2-/- mice had elevated basal levels of IL-10, which could be related to a lower risk of mortality during the acute phase of infection." (PMID 34784372, 2021). "Hence, C. coli could stably establish within the gastrointestinal tract of hma TLR4-deficient IL10-/- mice until 21 days post-infection." (PMID 32443576, 2020). "We also found that immunized IL-10-deficient mice had improved bacterial clearance upon intraperitoneal infection with S. aureus, and importantly, protection induced by genetic deficiency of IL-10 could be transferred to naïve mice by the adoptive transfer of CD4+ T cells." (PMID 33291260, 2020). "Also, the role IL-10 could have is based on genetic regulation because numerous polymorphisms have been associated to the IL-10 synthesis and receptors that may modulate the production of cytokines and may alter the risk of infection of HP." (PMID 32695157, 2020). "Also, since IL-4, IL-10, and IL-1Ra are known to play a detrimental role in enhancing susceptibility to infection, our data indicate that alteration of the balance between protective and regulatory cytokines plays a pivotal role in the establishment of cytokine responses in filarial-TBL coinfection." (PMID 32373129, 2020). "Considering the essential role of IL-10 in limiting the pathogenicity and, thus, the susceptibility to infection, we evaluated if besides leukocytes (i. e. regulatory T cells and myeloid cells) also hepatocytes could be a potential source of IL-10 during African trypanosome infection." (PMID 32012211, 2020). "Considered collectively, the discrepancies between the results of our study and others regarding IFN-γ and IL-10 expression may be associated with differences between in vivo and in vitro experiments, different infection target sites, and animal and disease models." (PMID 33175869, 2020). "Collectively, we observed that parasites can induce IL-10 production by hepatocytes and that hepatocyte-derived IL-10 is crucial to attenuate systemic inflammation and T. congolense infection-associated pathogenicity during the later stages of infection resulting in a prolonged survival." (PMID 32012211, 2020). "BALB/c is also highly susceptible to infection by L. major, with severe lesions and parasite-specific Th2 response with the enhanced expression of deactivating macrophage cytokines—particularly interleukin 4 (IL-4), interleukin 10 (IL-10), and transforming growth factor-β (TGF-β)." (PMID 32610603, 2020). "Moreover, TLR-2 stimulation polarizes IL-10 production causing persistence of infection." (PMID 33238997, 2020). "B-1 cells are producers of a variety of molecules, such as IL-10, IL-3, and GM-CSF, which are capable of exerting influence on other cell populations and thus may influence the susceptibility or resistance in models of infection." (PMID 31338088, 2019).
infection (continued). "Under these conditions, a reduced IL-8 expression was observed at 2 h post infection, whereas an increased IL-10 expression was detected at 6 h post infection, indicating that NF-κB activity causes a slight inhibition of IL-10 expression in BEC infected with S. aureus." (PMID 29434603, 2018). "In mammals, it has been widely described that IL-10 acts as a potent anti-inflammatory cytokine that regulates and inhibits the expression of pro-inflammatory cytokines, contributing to the normal resolution of infection and reducing tissue damage caused by inflammation." (PMID 29867929, 2018). "The role of interleukin-10 (IL-10) has been widely described as a potent anti-inflammatory cytokine that regulates the expression of pro-inflammatory cytokines, contributing to the pathogen infection resolution and also reducing tissue damage caused by inflammation." (PMID 29867929, 2018). "Conversely, susceptibility to infection and disease progression in CL is driven predominantly by the induction of a non-protective IL-4 Th-2-type response and the production of Th-2 associated cytokines such as IL-4, IL-10, IL-13 and transforming growth factor (TGF)-β." (PMID 27094260, 2017). "Therefore, we inferred that the protective effect of IL-10 polymorphisms on infection could confuse their influence on tacrolimus pharmacokinetics." (PMID 28246425, 2017). "IL-10 has been able to suppress NO production and leishmanicidal activities in the macrophages, leading to the suppression of Th1 response, resulting in the continuous progression of infection in susceptible mice and preventing the elimination of Leishmania (sterile cure) in resistant mice." (PMID 28848541, 2017). "Furthermore, the protection elicited by IL-17 against infection is associated with the downregulation of regulatory T cells and IL-10 production, while benefiting the Th1 response and improving the leishmanicidal activity of macrophages in an NO-dependent manner." (PMID 28747911, 2017). "Importantly, the adoptive transfer of T or B cells from WT mice restored the susceptibility of IL-10−/− mice to systemic S. Typhimurium infection, suggesting that the generation of regulatory cells in vivo is required to sustain a systemic infection by S. Typhimurium." (PMID 28824622, 2017). "Thus, NK cell IL-10 production may well impact human susceptibility to infections and other diseases, including Lm infection." (PMID 27295349, 2016). "We have previously utilized IL-10 reporter mice to identify the iregAPC, however this limits the ability to differentiate factors affecting their generation from functional changes or to elucidate the mechanisms underlying their suppressive capacity using other mouse and infection models." (PMID 26808628, 2016). "In the well-established model of infection of mice with L. major, resistance to several parasite strains is mediated by the development of a Th1 immune response, while susceptibility is characterized by the development of a Th2 response, or to production of IL-10." (PMID 27056545, 2016). "The fact that IL-10 and IL-17 both have been associated with the indeterminate form suggests that the induction of IL-17 by Col cl1.7 may also be associated with the more mild infection observed in experimental models, as compared to Y strain." (PMID 26147698, 2015). "Indeed, the low influx of PMN cells to the site of infection and the decreased production of TNF-α and IL-12 associated with enhanced production of IL-10 detected 48 h after infection of MLT-treated B10.A mice indicated a prevalent LX signaling when CysLTR1 was blocked." (PMID 26635449, 2015). "In addition, variations in IL-10 levels may be caused not only by ongoing or past infections, but by host-related factors as well." (PMID 25888883, 2015).